MUC7 (mucin 7, secreted)
Description:
May function in a protective capacity by promoting the clearance of bacteria in the oral cavity and aiding in mastication, speech, and swallowing. Binds P.aeruginosa pili.
Synonyms: MG2; FLJ27047
Tractability: Antibody: UniProt places it where antibodies can reach, with high confidence; its Gene Ontology location is reachable by antibodies, with high confidence; UniProt predicts a signal peptide or a membrane-spanning region.
Gene: Protein-coding gene on chromosome 4 (70,430,492 to 70,482,997, forward strand). Ensembl gene ENSG00000171195.
Subcellular location: Secreted
Pathways (Reactome):
Disease: Defective C1GALT1C1 causes TNPS; Defective GALNT12 causes CRCS1; Defective GALNT3 causes HFTC
Metabolism of proteins: O-linked glycosylation of mucins; Termination of O-glycan biosynthesis
Immune System: Dectin-2 family
Gene Ontology:
Molecular function: protein binding
Biological process: antimicrobial humoral immune response mediated by antimicrobial peptide; killing of cells of another organism
Cellular component: extracellular exosome; Golgi lumen; plasma membrane; extracellular region
Genetic constraint (gnomAD): Loss-of-function variants: 2 observed, 3.15 expected, observed/expected ratio (o/e) 0.63, 90% interval 0.25 to 1.7. That is too few expected variants to judge how well the gene tolerates losing a copy. Missense variants: 408 observed, 465.05 expected, observed/expected ratio (o/e) 0.88, 90% interval 0.81 to 0.95. Synonymous variants: 133 observed, 181.45 expected, observed/expected ratio (o/e) 0.73, 90% interval 0.64 to 0.85.
Homologues: Orthologues: chimpanzee MUC7 (92% identical), macaque MUC7 (84% identical).
Diseases named in the same sentence as MUC7 in open-access papers:
MUC7 is named in the same sentence as 46 diseases in open-access papers, as found by Europe PMC text mining. Sharing a sentence is not in itself a finding about the gene and the disease. The quoted sentences say what the papers report.
asthma (5 papers, 2012 to 2023). "MUC7 codes for salivary mucin;the frequency of the MUC7 allele with five tandem repeats is significantlyreduced in patients with asthma." (PMID 37153512, 2023). "Asthma patients displayed significantly fewer frequency of 6*5 genotype of the MUC7 VNTR variant than controls (14% vs. 29%; OR = 0.25 and 95% CI = 0.16–0.75, p = 0.045)." (PMID 36344553, 2022). "Further, a later study announced that the MUC7*5 allele is associated with a lowered risk of a diagnosis of asthma in an African American population." (PMID 36344553, 2022). "MUC7 is overexpressed in the minor salivary gland and has been associated with asthma." (PMID 28974199, 2017). "Genetic polymorphism of MUC7 alleles has been shown to be associated with asthma in which a shorter MUC7 allele has protective properties and a longer MUC2 allele may help protect atopic individuals." (PMID 22929306, 2012).
bladder cancer (3 papers, 2017 to 2023). "MUC7 has often been associated with other cancer types, particularly bladder cancer, and its expression levels have been assayed in many tumor types." (PMID 35751785, 2022).
Sjögren’s syndrome (3 papers, 2019 to 2021). "Reduced sialylation of MUC7 has also been demonstrated in Sjögren’s syndrome patients and may be associated with decreased lubrication and protection of the oral mucosa." (PMID 31554163, 2019). "Key words:Primary Sjögren's syndrome, mucin, MUC7, MUC5B, MUC1, sulphate oligosaccharides." (PMID 33247578, 2021). "It is a common opinion that Primary Sjögren Syndrome (pSS) damages the exocrine glands and determines the reduction of secreted saliva, some studies show that there are qualitative anomalies of the mucins produced in saliva, including MUC7, MUC5B, MUC1." (PMID 33247578, 2021).
AIDS (2 papers, 2006 to 2010). A syndrome resulting from the acquired deficiency of cellular immunity caused by the human immunodeficiency virus (HIV). "The purpose of this subsequent study was to investigate whether MUC5B and MUC7 from saliva of HIV patients or with full blown AIDS had a similar inhibitory activity against the virus." (PMID 20946627, 2010). "With this in mind, we decided to investigate whether MUC5B and MUC7 from saliva of HIV patients or with full blown AIDS had a similar inhibitory activity, as the MUC5B and MUC7 from HIV negative individuals, against the virus." (PMID 20946627, 2010).
HIV-1 infection (2 papers, 2006 to 2008). The type species of lentivirus and the etiologic agent of acquired immunodeficiency syndrome (AIDS). "This was supported by our finding that salivary MUC7 inhibited HIV-1 infection of the CEM SS cells when it was incubated with the virus prior to addition to the CEM SS cells." (PMID 18489743, 2008). "The result revealed that after a 30 min incubation period during which the mixtures three separate mixtures (HIV-1 plus crude saliva), (HIV-1 plus MUC5B) and (HIV-1 plus MUC7) were incubated with the CD4+ CEM SS cells, no HIV-1 infection of these cells was observed." (PMID 17125499, 2006).
Nasal Polyps (2 papers, 2022). "did not detect MUC7 mucin in 26 samples of nasal polyps, while its expression was confirmed in 6 out of 11 normal mucosa samples, which was restricted to glands." (PMID 36059464, 2022). "hsa-mir-27a-3p may promote the occurrence of inflammation and the formation of nasal polyps by regulating the expression of AZGP1, NCF2, CCL13, MUC7, PIP, and STATH." (PMID 36059464, 2022).
bacterial vaginosis (1 paper, 2016). Infection caused by bacterial overgrowth in the vagina. "In this study we report the changes in membrane bound (MUC1 and MUC4) and gel-forming mucins (MUC5AC and MUC7) relative to the influence of hormones and the presence of the abnormal vaginal flora of bacterial vaginosis." (PMID 27437931, 2016).
cholangiocarcinoma (1 paper, 2023). A carcinoma that arises from the intrahepatic biliary tree (intrahepatic cholangiocarcinoma) or from the junction, or adjacent to the junction, of the right and left hepatic ducts (hilar cholangiocarcinoma). "MUC1 showed high expression in cholangiocarcinomas and cholangiocellular differentiated areas of cHCC-CCC, whereas MUC2, MUC3, MUC5/6, MUC5AC, MUC6, and MUC7 showed limited usefulness for further differentiation." (PMID 36672443, 2023).
chronic pancreatitis (1 paper, 2024). A chronic inflammatory process causing damage and fibrosis of the pancreatic parenchyma. "On the other hand, MUC7 is significantly less specific as a diagnostic biomarker, since it was also found to be upregulated in IPMN and chronic pancreatitis." (PMID 39767746, 2024).
cyst (1 paper, 2011). A sac-like closed membranous structure that may be empty or contain fluid or amorphous material. "The search for more dependable cyst fluid biomarkers than CEA continues: most recently MUC7 was found to have significant value in determining likelihood of a need for surgery and malignant potential of cysts." (PMID 22047595, 2011).
head and neck cancer (1 paper, 2021). A primary or metastatic malignant neoplasm affecting the head and neck. "The aim of the study was therefore to determine over time changes of total protein and IgA as well as mucin type O-linked glycans (mostly MUC5B and MUC7) in stimulated whole saliva in relation to dry mouth and sticky saliva in head and neck cancer patients." (PMID 34627217, 2021). "From the gel separation prior to the MS-analysis it was seen that MUC7 was only detected in low abundance and in many cases not at all, which in congruence with the results with a previous study where no MUC7 in unstimulated saliva from head and neck cancer patients pretreatment was found." (PMID 34627217, 2021).
Insulin resistance (1 paper, 2025). Increased resistance towards insulin, that is, diminished effectiveness of insulin in reducing blood glucose levels. "Additionally, protein RBP4, a well-known adipokine associated with insulin resistance in T2D, and mucin (MUC7) were upregulated, serving as quality controls for our analysis." (PMID 39794871, 2025).
lung carcinoma (1 paper, 2022). "MUC7 was related to cell differentiation in smoke-induced lung cancer." (PMID 36059804, 2022).
lung disease (1 paper, 2011). "These were MUC1, MUC2, MUC5AC and MUC7 whose encoded proteins are of recognized importance in normal airway defense, and/or prior studies that indicate they play a role in diseases of the lung, and other inflammatory or malignant disease." (PMID 21998660, 2011).
oral candidiasis (1 paper, 2007). Infection of the mucosal lining of the mouth with the fungus Candida albicans. "This suggests that MUC7 12-mer peptide is active for oral candidiasis in oral physiological conditions." (PMID 17996119, 2007).
oral diseases (1 paper, 2010). "For instance MUC7 in immunocompromised individuals is reported to lose the expression of sugar receptor (sLex) hence making the individual more susceptible to oral diseases." (PMID 20946627, 2010).
oral squamous cell carcinoma (1 paper, 2025). "Complementing our study similar transcriptomic studies reported STATH and MUC7 are downregulated hub genes that regulate key pathways in oral squamous cell carcinoma (OSCC), a major subtype of HNSCC." (PMID 41552085, 2025).
ovarian carcinoma (1 paper, 2025). A malignant neoplasm originating from the surface ovarian epithelium. "Our regression analysis identified six genes significantly associated with ovarian cancer: PI3, TFAP2B, MUC7, PSMA2, PIK3C2G, and NME1." (PMID 41154754, 2025).
prostate carcinoma (1 paper, 2023). A carcinoma that arises from epithelial cells of the prostate gland. "Comparing the mutations in pre- and post- resistant samples, we also fund that MUC7 and MUC5B mutation repair may be associated with longer PFS and ZNF91 mutation may be a key factor contributing to the development of drug resistance in prostate cancer." (PMID 37726835, 2023).
psoriasis (1 paper, 2012). An autoimmune condition characterized by red, well-delineated plaques with silvery scales that are usually on the extensor surfaces and scalp. "Several genes in the psoriasis classifier, KYNU (up), MUC7 and CLDN8 (down), were part of the Etanercept “molecular scar” previously reported by our group." (PMID 22957057, 2012).
pterygium (1 paper, 2021). A wedge-shaped fibrovascular lesion arising from the bulbar conjunctiva and extending to the cornea. "MUC7 expression was downregulated in pinguecula, and even more in pterygium-NE, and was one of the top downregulated DEGs in pterygium-E." (PMID 34769520, 2021). "MUC7 expression was downregulated in pinguecula and was one of the top downregulated genes in pterygium." (PMID 34769520, 2021).
stomach cancers (1 paper, 2017). "Examining a possible role with altered expression of MUC7 is further confounded by small sample sizes of different histological subtypes in multiple cancers, including BRCA and stomach cancers cohorts." (PMID 28978023, 2017).
triple-negative breast carcinoma (1 paper, 2017). An invasive breast carcinoma which is negative for expression of estrogen receptor (ER), progesterone receptor (PR), and human epidermal growth factor receptor 2 (HER2). "There is also a questionable status of MUC7 expression in BRCA, in which most histological subtypes appear to have some specimens without MUC7 expression after normalization; however, triple negative breast cancer and low sample size confounds the analysis of MUC7 in BRCA." (PMID 28978023, 2017).
viral infection (1 paper, 2010). "Unlike the filtrates from the mixtures of HIV-1 plus MUC5B and MUC7 from HIV negative individuals, these filtrates caused 100% viral infection of the CEM SS cells." (PMID 20946627, 2010). "The result demonstrated that irrespective of their CD4 count both MUC5B and MUC7 mucins from HIV patients, unlike those HIV negative patients, failed to inhibit HIV-1 activity and a 100% viral infection of the CEM SS cells was measured by the p24 antigen assay after a 30 min incubation period." (PMID 20946627, 2010).
tumor (13 papers, 2004 to 2025). "We observed a decrease in the expression of genes encoding membrane-bound MUC15 and secreted MUC7 and MUC19 in tumor samples (p < 0.01)." (PMID 33182511, 2020). "Both MUC7 and MUC5B are members of the mucin family, overexpression and abnormal glycosylation of some transmembrane mucins in adenocarcinoma are associated with aggressive tumor proliferation and poor patient prognosis." (PMID 37726835, 2023). "Our analyses revealed elevated levels of MUC7 and MUC16 in the saliva of patients with OSCC compared with controls, indicating their role in tumor progression." (PMID 37686462, 2023). "Of these 7 survival-related genes, CSN3, KRT81, MUC7, and MYH6 has been elucidated to take part in tumor progression." (PMID 33530209, 2021). "Tumor microenvironment related genes ADGRG7, CSN3, CST8, KRT81, MUC7, MYH6, and SEZ6 are valuable predictors for HNSCC patient survival." (PMID 33530209, 2021). "Interestingly, there were four tumor suppressors significantly stimulated after YB, namely, deleted in malignant brain tumor 1 (DMBT1), mucin-7 (MUC7), cysteine-rich secretory protein 3 (CRISP3), and prolactin-inducible protein (PIP)." (PMID 25873979, 2015).
infection (8 papers, 2006 to 2025). The state of being infected such as from the introduction of a foreign agent such as serum, vaccine, antigenic substance or organism. "MUC7 encodes a small salivary mucin protein that protects T cells and epithelial cells from infection by binding antimicrobial proteins to retain them in the oral cavity." (PMID 36059464, 2022). "PCR was done on tandem repeat regions of MUC5B and MUC7 DNA to investigate whether any association existed between gene polymorphism and susceptibility to infection." (PMID 22929306, 2012). "An investigation of the variation in the genetic and protein structure of mucins MUC5B and MUC7 and their association with infection with HIV is a study that could be engendered by these findings." (PMID 22929306, 2012). "Indeed, the polymorphisms within MUC5B and MUC7 genes may play a role in the susceptibility to infection (by viruses such as HIV)." (PMID 22929306, 2012). "This suggests a potential for MUC7 12-mer as a chemotherapeutic agent for the systematic infection with E. coli without being affected at physiological salt concentrations." (PMID 17996119, 2007). "However, the differences in MUC5B and isoforms of MUC7 are not entirely explainable by the infection itself." (PMID 33224896, 2020). "Although mucins MUC7 and MUC5AC were strongly downregulated in response to infection, consistent with our results at baseline, we found little evidence in this study for dysregulation of mucins (hypothesized to lead to loss of epithelial barrier function) being associated with scarring progression." (PMID 31964744, 2020). "The inhibitory activity of crude saliva and purified MUC5B and MUC7, from HIV negative (n=20) and HIV positive (n=20) donors, was tested by their incubation with subtype C HIV-1 and subsequent infection of peripheral blood mononuclear cells (PBMCs)." (PMID 22929306, 2012). "In this study we have demonstrated that when the HIV-1 was incubated with the crude saliva and purified salivary MUC5B and MUC7 mucins and subsequently added to the CD4+ CEM SS cells no viral replication or infection of the CEM SS cells was detected by the p24 antigen assay." (PMID 17125499, 2006).
cancer (6 papers, 2015 to 2024). A tumor composed of atypical neoplastic, often pleomorphic cells that invade other tissues. "The relative abundance of Mucin MUC7 tended to be lower in the cancer patients both at pre-treatment and at 6 months post-treatment compared with healthy controls, which is in accordance with previous studies." (PMID 39640734, 2024). "Tendencies to lower relative abundances of Cystatin S (p = 0.05), Cystein-rich secretory protein 3 (p = 0.06), and Mucin MUC7 (p = 0.07) in the cancer patients were also detected." (PMID 39640734, 2024). "The relative abundance of mucin MUC7 tended to be decreased in the cancer patients compared with the healthy controls, which might be of importance for patients’ experience of dry mouth, sticky saliva and swallowing difficulties." (PMID 39640734, 2024). "Still, the observed increase in MUC7 expression might lead to a possible novel marker in cancers." (PMID 28978023, 2017). "Saliva from the cancer patients showed a low abundance/no detectable MUC7, while the MUC5B level remained, compared to saliva from a healthy control." (PMID 34627217, 2021). "MUC7 appears to have little to no expression in many cancer tissues." (PMID 28978023, 2017).
bacterial infections (2 papers, 2007 to 2021). "Similarly, the higher presence in S/SEV_FREE of MUC 5, MUC7, and MUC16 may indicate a condition in which the oral mucosa of OSCC_FREE subjects is more protected from bacterial infections that are strictly related to oral carcinogenesis." (PMID 34681822, 2021).
MUC7 also shares sentences with these, for which no sentence is quoted: dental caries (3 papers); adenocarcinoma (2); breast carcinoma (2); autosomal dominant tubulointerstitial kidney disease (1); bronchiectasis (1); chronic bronchitis (1); cystic fibrosis (1); diverticulosis (1); ductal adenocarcinoma (1); intraductal papillary mucinous neoplasm (1); Kartagener Syndrome (1); kidney disease (1); Obesity (1); ovarian clear cell cancer (1); periodontitis (1); pseudomyxoma peritonei (1); urinary tract infection (1); xerostomia (1).